CNR2 (cannabinoid receptor 2)
Diseases named in the same sentence as CNR2 in open-access papers (continued):
Sharing a sentence is not in itself a finding about the gene and the disease.
Alzheimer disease (24 papers, 2014 to 2025). A progressive, neurodegenerative disease characterized by loss of function and death of nerve cells in several areas of the brain leading to loss of cognitive function such as memory and language. "Cannabinoid receptor 2 in microglia appears to be involved in a variety of paradigms and diseases involving neuroinflammation, including Alzheimer’s disease (AD), Parkinson’s disease, multiple sclerosis (MS), as well as stress or addiction." (PMID 35492718, 2022). "Interestingly, in the transgenic mice model of Alzheimer’s disease, APPswe/PS1dE9 mice, CNR2 expression reduced at 6-months of age while statistical significance was notified at 12-months." (PMID 35682586, 2022). "Cannabinoid receptor-2 has shown therapeutic potential as a target against HAND and other CNS disorders, such as Alzheimer’s disease (AD), amyotrophic lateral sclerosis (ALS), Parkinson’s disease (PD), multiple sclerosis (MS), Huntington’s disease (HD), neuropathic pain, and migraine." (PMID 41226631, 2025).
osteoporosis (22 papers, 2008 to 2025). A condition of reduced bone mass, with decreased cortical thickness and a decrease in the number and size of the trabeculae of cancellous bone (but normal chemical composition), resulting in increased fracture incidence. "Two SNPs of rs2501431 and rs4237 in CNR2 gene may be indicative of the risk of osteoporosis in Chinese postmenopausal women." (PMID 33512770, 2021). "Furthermore, bone marrow samples showed that the expression of CNR2 is much lower in patients with osteoporosis than healthy donors: CNR2 deficiency may be related to osteoporosis." (PMID 37675799, 2023). "We found specific osteoporosis-linked SNPs in genes encoding key receptors involved in bone metabolism that are classified into rhodopsin (ADRB2, CNR2, MTNR1B, FSHR, TSHR, LGR4), secretin (CALCR, GIPR), and other T7M (WLS) receptor families." (PMID 39769358, 2024). "Osteoporosis and cancer are both progressive, aging-associated diseases and CNR2/CB2 activity protects against both diseases." (PMID 36835468, 2023). "An earlier study demonstrated that mice with CNR2 knockout had a reduced bone mass, reminiscent of human osteoporosis." (PMID 33512770, 2021). "Notably, the involvement of CNR2 provides a new direction for exploring the mechanism by which TPhP induces osteoporosis." (PMID 40692598, 2025). "The LASSO regression algorithm established an osteoporosis-related model, identifying six disease-related candidate core target genes (IGF1R, NR3C1, MAP3K1, BRAF, WNK4, CNR2)." (PMID 40692598, 2025). "Moreover, it has also been demonstrated that CNR2 activation in hFOB 1.19 cells was able to increase their ALP activity and the production of a mineralized bone matrix, and that polymorphisms of the gene encoding for CNR2 are highly correlated with the occurrence of osteoporosis." (PMID 39940911, 2025).
multiple sclerosis (21 papers, 2006 to 2025). A progressive autoimmune disorder affecting the central nervous system resulting in demyelination. "Furthermore, an association has been observed between multiple sclerosis and the single-nucleotide polymorphism Q63R in the CNR2 gene coding for the CB2R functional variation." (PMID 36551756, 2022). "Activation of cannabinoid receptor 2 (CB2) decreases inflammatory responses and the production of proinflammatory cytokines and is protective in mouse models of neurodegenerative diseases, including multiple sclerosis, ALS, and Parkinson's disease." (PMID 25873774, 2015).
colon carcinoma (17 papers, 2013 to 2025). "As we previously found common CNR2 variants are associated with colon cancer in humans and data from mice experiments shows a role of CB2 in immune-cell modulation, we evaluated common and rare variants associated with monocyte count." (PMID 40307509, 2025). "Taken together, the results suggest that endogenous CB2 activation suppresses colon tumorigenesis by shifting the balance towards anti-tumor immune cells in mice and thus portray the prognostic value of CNR2 variants for colon cancer patients." (PMID 36835468, 2023). "Recently, we reported on the protective role of CB2 in colon cancer and found that colon cancer incidence in humans is significantly associated with polymorphism in the CNR2 gene encoding for CB2." (PMID 37175480, 2023). "Here, we investigate the role of CB2 in potentiating the immune response in colon cancer in mice and determine the influence of CNR2 variants in humans." (PMID 36835468, 2023). "Indeed, corroborative data from a large human population databank (UK Biobank) reveal a significant association between non-synonymous variants of CNR2 and colon cancer incidence in humans." (PMID 36835468, 2023). "Importantly, corroborative genomic data reveal a significant association between non-synonymous variants of CNR2 and the incidence of colon cancer in humans." (PMID 36835468, 2023). "Additionally, we analyzed genomic data in a large human population to determine the relationship between CNR2 variants and colon cancer incidence." (PMID 36835468, 2023). "The endocannabinoid system, particularly cannabinoid receptor 2 (CB2 in mice and CNR2 in humans), has controversial pathophysiological implications in colon cancer." (PMID 36835468, 2023).
atherosclerosis (16 papers, 2011 to 2025). A disease characterized by the build-up of fatty material and calcium deposition in the arterial wall resulting in partial or complete occlusion of the arterial lumen. "Strong evidence supports a protective role of the cannabinoid receptor 2 (CB2) in inflammation and atherosclerosis." (PMID 21541300, 2011).
melanoma (16 papers, 2014 to 2024). A malignant, usually aggressive tumor composed of atypical, neoplastic melanocytes. "In this study we investigated the role of cannabinoid receptor 2 (CB2R) on immune cells in melanoma and found significantly improved overall survival in patients with high intra-tumoral CB2R gene expression." (PMID 33923757, 2021). "Given recent evidence that cannabinoid receptor 2 (CB2R) regulates lymphocyte development and inflammation, we performed studies on CB2R in the immune response against melanoma." (PMID 33923757, 2021).
liver disease (15 papers, 2012 to 2024). "The endocannabinoid system plays an essential role in the regulation of analgesia and human immunity, and Cannabinoid Receptor 2 (CB2) has been proved to be an ideal target for the treatment of liver diseases and some cancers." (PMID 34771087, 2021). "Cannabinoid receptors 1 (CB1) and cannabinoid receptor 2 (CB2) are two G-protein receptors identified within the endocannabinoid system that may play a role in liver disease." (PMID 29890719, 2018). "Within it, two specific G-protein receptors have been identified that may play a role in liver disease, namely, cannabinoid receptor 1 (CB1) and cannabinoid receptor 2 (CB2)." (PMID 34298967, 2021).
rheumatoid arthritis (15 papers, 2014 to 2025). A chronic, systemic autoimmune disorder characterized by inflammation in the synovial membranes and articular surfaces. "In a murine model of RA, another cannabinoid receptor 2 agonist JWH-015 demonstrated inhibition of pro-inflammatory cytokine interleukin-1β-induced inflammation in rheumatoid arthritis synovial fibroblasts partly via a glucocorticoid receptor." (PMID 34502379, 2021).
steatosis (15 papers, 2009 to 2025). Increased lipid within the cytoplasm of cells. "For example, in studies of obese children with steatosis and biopsy-proven NAFLD, a functional variant of the otherwise hepatoprotective cannabinoid receptor 2 (CB2), Q63R, was associated with elevated serum aminotransferase levels." (PMID 27314342, 2016). "In contrast, HFD-fed Cnr2 −/− animals exhibited minimal steatosis, as illustrated by the decrease in the steatosis score and the decline in liver triglyceride concentration, compared to HFD-fed WT animals." (PMID 19513120, 2009). "On the other hand, in Cnr2 −/− HFD-fed mice model, the absence of CB2 receptors decreases the steatosis and liver triglyceride concentration caused by HF diet, suggesting that CB2 activation contributes to liver inflammation and hepatic steatosis." (PMID 30282988, 2018).
Arthritis (14 papers, 2014 to 2025). Inflammation of a joint. "Cannabinoid receptor 2 (CB2) has powerful anti-inflammatory effects, and a selective agonist of CB2, 4-quinolone-3-carboxamides (4Q3C), can significantly improve arthritis and reduce bone erosion." (PMID 37298893, 2023). "In the present study, we evaluated the efficacy of cannabinoid receptor 2 (CB2) agonist JWH-015 using RA synovial fibroblasts (RASFs) obtained from patients diagnosed with RA and in a rat adjuvant-induced arthritis (AIA) model of RA." (PMID 31139184, 2019).
prostate carcinoma (14 papers, 2009 to 2025). A carcinoma that arises from epithelial cells of the prostate gland. "In addition to close collaboration with CXCR7, using biophysical and biochemical methods, CXCR4 is found to form induced heterodimers with the cannabinoid receptor 2 (CB2) in human breast and prostate cancer cells." (PMID 41347146, 2025).
Sepsis (14 papers, 2009 to 2025). Sepsis is defined as life-threatening organ dysfunction caused by a dysregulated host response to infection. "And the effects of cannabinoid receptor 2 (CB2R) on the sepsis still remain undefined." (PMID 23781122, 2013). "Cannabinoid receptor 2 (CB2R) expression is upregulated during sepsis." (PMID 22420504, 2012).
Stroke (14 papers, 2010 to 2025). Sudden impairment of blood flow to a part of the brain due to occlusion or rupture of an artery to the brain. "In a recent clinical study, we reported a significant elevation of the percentage of CD14++/CD16+ intermediate and CD14+/CD16+ non-classical monocyte subsets, as well as their relative expression of the cannabinoid receptor-2 (CB2), 24 and 48 h after stroke." (PMID 34201498, 2021).
liver fibrosis (13 papers, 2010 to 2024). "The activation of cannabinoid receptor 2 (CB2) in the liver can improve liver fibrosis caused by bile duct ligation and promote liver regeneration." (PMID 38397045, 2024).
Cognitive impairment (12 papers, 2012 to 2025). Abnormal cognition is characterized by deficits in thinking, reasoning, or remembering. "We compared the cognitive impairment induced by hTAUP301L between wild type (Cnr2+/+) and CB2-knockout (Cnr2−/−) mice and the results were correlated with the phosphorylation and aggregation status of TAU." (PMID 34001284, 2021).
diabetes (12 papers, 2010 to 2025). "The CNR2 gene in locus 1p36.1 (SNP rs542405361, p = 9.43 × 10–6) has been associated with diabetic nephropathy, kidney fibrosis and diabetes-induced cardiac dysfunction, all phenotypes associated with DKD52–54." (PMID 36949158, 2023).
Insulin resistance (12 papers, 2009 to 2024). Increased resistance towards insulin, that is, diminished effectiveness of insulin in reducing blood glucose levels. "HFD-induced insulin resistance increased in response to JWH-133 and reduced in Cnr2 −/− mice." (PMID 19513120, 2009).
lung carcinoma (12 papers, 2016 to 2024). "Additionally, M2-like TAMs secrete EGF-like ligands to activate EGFR pathway in lung cancer cells, which ultimately promoting EMT that can be inhibited by a cannabinoid receptor 2 (CB2) agonist JWH-015 via downregulation of EGFR signaling." (PMID 28467800, 2017).
Parkinson disease (12 papers, 2015 to 2025). A progressive degenerative disorder of the central nervous system characterized by loss of dopamine producing neurons in the substantia nigra and the presence of Lewy bodies in the substantia nigra and locus coeruleus. "GWAS studies indicates that the CNR2 gene is associated with Parkinson’s disease and substance use disorders." (PMID 29234141, 2017). "The results of the meta-analysis of three dbGaP GWAS datasets for CNR2 nominal association with Parkinson’s disease show a signal in 3′UTR, rs4474201 (p = 0.02175, OR = 0.91." (PMID 29234141, 2017). "Furthermore, human CNR2 gene is potentially associated with substance use disorders and Parkinson′s disease." (PMID 29234141, 2017).
autoimmune disease (11 papers, 2019 to 2025). A disorder resulting from loss of function or tissue destruction of an organ or multiple organs, arising from humoral or cellular immune responses of the individual to their own tissue constituents. "For example, the polymorphism in cannabinoid receptor 2 associated with reduced endocannabinoid effects is more prevalent in autoimmune diseases, including MS." (PMID 39114536, 2024). "Human specific CNR2 isoforms are induced by inflammation in pancreatic islets, and a CNR2 nonsynonymous SNP (Q63R) is associated with autoimmune diseases." (PMID 35115945, 2021).
colorectal cancer (10 papers, 2015 to 2025). A primary or metastatic malignant neoplasm that affects the colon or rectum. "Cannabinoid receptor 2 may have an effect on colorectal cancer‐associated skeletal MA." (PMID 39743857, 2025).
neuropathy (10 papers, 2010 to 2025). A disorder affecting the nervous system that manifests with pain, tingling, numbness, and/or muscle weakness. "We analyzed genes known to be targeted by cannabigerol and other cannabinoids, including Cnr1, Cnr2, Gpr55, Faah, Mgll, Adra2a-c, Pparg, or to have been previously published as volatile in a cisplatin-induced neuropathy setting in DRG, including Drd2, Gfap, and Oprm1." (PMID 37895913, 2023).
Hepatic steatosis (9 papers, 2009 to 2024). Steatosis is a term used to denote lipid accumulation within hepatocytes. "Finally, HFD-induced hepatic steatosis was enhanced in WT mice treated with JWH-133 and blunted in Cnr2 −/− mice." (PMID 19513120, 2009).
myocardial infarction (9 papers, 2017 to 2024). Gross necrosis of the myocardium, as a result of interruption of the blood supply to the area, as in coronary thrombosis. "Cannabinoid receptor 2 (CB2) has been reported to produce a cardio-protective effect in cardiovascular diseases such as myocardial infarction." (PMID 30459625, 2018). "In a study performed on mice with permanent CAO, the selective cannabinoid receptor-2 (CB2) agonists JWH-133 (10 mg/kg) decreased the IS/AAR ratio by about 33% and improved cardiac contractility 6 hours after myocardial infarction." (PMID 36320147, 2022). "Cannabinoid receptor 2 (CB2R) has been reported to play an important role in the regulation of pathogenesis and progression of myocardial infarction (MI)." (PMID 30923227, 2019).
non-small cell lung carcinoma (9 papers, 2017 to 2025). A group of at least three distinct histological types of lung cancer, including non-small cell squamous cell carcinoma, adenocarcinoma, and large cell carcinoma. "Our studies are in accordance with previous studies, which showed that CNR2 agonists inhibit the tumor growth and metastasis through induction of apoptosis and inhibition of EGFR activation in non-small cell lung cancer (NSCLC)." (PMID 27213582, 2017).
renal fibrosis (9 papers, 2018 to 2025). A final common manifestation of a wide variety of chronic kidney diseases characterized by glomerulosclerosis and tubulointerstitial fibrosis. "Celastrol also protects against renal fibrosis through upregulating the cannabinoid receptor 2, improving cardiac fibrosis through inhibiting microRNA-21/ERK1/2, and improving pulmonary fibrosis through activating autophagy." (PMID 37005411, 2023). "In terms of cannabinoid receptor 2 expression, UUO- or TGF-β1-induced renal fibrosis can be attenuated via upregulation of CB2." (PMID 37772226, 2023).
atopic dermatitis (8 papers, 2012 to 2025). "To achieve this goal, we tested c-kit, Ki67, and cannabinoid receptor 2 on several cases of cutaneous canine mast cell tumors (MCTs), cutaneous mastocytosis, and atopic dermatitis." (PMID 34679059, 2021).
breast tumor (7 papers, 2009 to 2026). "The plant’s interaction with cannabinoid receptor 2 (CB2), which is overexpressed in breast tumor cells, supports its therapeutic relevance." (PMID 41599692, 2026).
injury (7 papers, 2010 to 2025). Damage inflicted on the body as the direct or indirect result of an external force, with or without disruption of structural continuity. "Because nerve injury also causes DNA methylation reprogramming in the DRG and because DNA methylation controls gene expression, we conducted additional experiments to determine whether nerve injury alters DNA methylation status of Cnr2 in the DRG." (PMID 35500651, 2022).
Cerebral ischemia (6 papers, 2010 to 2022). Restriction of arterial blood supply to the brain associated with insufficient oxygenation to support the metabolic requirements of the tissue. "Increased expression of inflammation makers and neuronal damage after focal cerebral ischemia in tMCAO mice mRNA levels were measured to address the question whether mouse non-ischemic and ischemic hemispheres differ in their expression levels of CNR2 and other inflammatory genes." (PMID 34642898, 2022).
COVID-19 (6 papers, 2020 to 2026). A disease caused by infection with severe acute respiratory syndrome coronavirus 2. "Lastly, gene expression of CB2 cannabinoid receptors CNR2 was raised in GCs-treated COVID-19 individuals compared to control, and there was a trend toward increased expression of CNR1." (PMID 36851787, 2023). "Several studies suggest that cannabidiol (CBD) may be useful in the treatment of patients with COVID-19 by inhibiting the expression of the protein critical for SARS-CoV2 virus replication and by binding as an agonist to the cannabinoid receptor 2 (CB-2), thus reducing inflammation and lung damage." (PMID 36556483, 2022).
eating disorder (6 papers, 2010 to 2026). A broad group of psychological disorders with abnormal eating behaviors leading to physiological effects from overeating or insufficient food intake. "So far, there is only one study on human genetic association to identify whether the CNR2 gene is involved in eating disorders." (PMID 35055161, 2022). "So far, there is only one study done on human genetic association to identify whether the CNR2 gene is involved in eating disorders." (PMID 35774086, 2022).
endometriosis (6 papers, 2019 to 2025). The growth of functional endometrial tissue in anatomic sites outside the uterine body. "In-vitro validation of CNR2 deficiency on CD3 T cell viability and functionality in conditions representative of Endometriosis (EM) lesion microenvironment." (PMID 39120997, 2024). "Compared with normal ovary (1.00), expression of CNR2 was significantly higher in endometriosis (1.94 − fold ± 0.05, P < 0.05)." (PMID 35692500, 2022). "Transcriptomic profiling of endometriosis-like lesions from canonical receptors (CNR1 and CNR2) knockout mice reveals extensive differential gene expression and altered pathways." (PMID 39120997, 2024).
fibrosis (6 papers, 2013 to 2021). the formation of excess fibrous connective tissue in an organ or tissue in a reparative or reactive process. "Although the effects of cannabinoids on lung fibrosis are not clear, a recent study showed that activation of cannabinoid receptor 2 (CB2) protects against bleomycin-induced fibrosis." (PMID 34884756, 2021).
lung fibrosis (6 papers, 2019 to 2025). "HU-308 (specifically binds to Cannabinoid receptor 2) attenuates lung fibrosis by inhibiting BLM-induced polarization of mouse Th2 cells through the specific activation of Cannabinoid Receptor 2 (CB2) on CD4+T cells." (PMID 40433386, 2025). "CNR2 agonists WIN55,212 and JWH-133 prevented skin and lung fibrosis in mice injected with hypochlorite, a murine model of SSc." (PMID 34830489, 2021).